IL6 (interleukin 6)
Diseases named in the same sentence as IL6 in open-access papers (continued):
Sharing a sentence is not in itself a finding about the gene and the disease.
Splenomegaly (66 papers, 2007 to 2026). Abnormal increased size of the spleen. "HHV-8 infection drives the expression of interleukin 6 (IL-6), leading to symptoms such as splenomegaly, and is associated with other diseases like primary effusion lymphoma (PEL) and Multicentric Castleman’s disease (MCD)." (PMID 39519059, 2024). "Our results showed that the LPS-exposed mice displayed a significant weight loss, a temperature increase, splenomegaly, hemorrhage, pulmonary hyperemia, and an increase in serum levels of IL-6." (PMID 32724488, 2020). "Previous studies have also found an association between splenomegaly and IL-6 and TNF-α." (PMID 39364261, 2024). "This compound also showed preferable anti-inflammatory activity in vivo, including alleviating significantly gastric distention and splenomegaly caused by LPS stimulation, reducing the level of oxidative stress induced by LPS, and inhibiting the expression of IL-6 and TNF-α in serum." (PMID 37325874, 2023). "Previously, it has been shown that HHV-8-encoded IL-6 induces splenomegaly." (PMID 22200846, 2012). "PLO treatment also mitigated IMQ-induced splenomegaly, and suppressed IL-1b and IL-6 expression in the spleen, and reduced IL-6 expression in the axillary lymph nodes." (PMID 42306466, 2026). "Our patient’s clinical picture, recurrent fever, mild splenomegaly, systemic inflammation, and elevated proinflammatory markers (IL-1β, IL-6, serum amyloid A), aligns with the phenotype of patients exhibiting complete loss of DOCK11 expression." (PMID 41250716, 2025). "GP63-VLPs inhibited the influx of pro-inflammatory cytokines IFN-γ and IL-6 in the livers, as well as thwarting the development of splenomegaly in immunized mice." (PMID 38857253, 2024). "The increase of IL-1β and IL-6 is consistent with a systemic inflammatory trigger preceding the phenotypes described earlier (UD and splenomegaly)." (PMID 37400834, 2023). "At Day 13 p.i., CHXscr mice exhibited reduced tumour‐free body weight (−22%), a prominent reduction in adipose tissue‐ and skeletal muscle weights, marked splenomegaly, and high plasma IL‐6 concentrations." (PMID 36351437, 2023). "In these animals, splenomegaly was accompanied by higher bacterial burden and higher levels of the pro-inflammatory cytokines IL-6, CXCL1, and MCP-1." (PMID 35248004, 2022). "As for splenomegaly, serum IL-6 levels were significantly higher in the patients with the lesions than in those without the lesions (53.2 [29.1–187.3] vs. 15.6 [7.4–74.4] pg/mL, p = 0.04)." (PMID 36494453, 2022). "In the elderly-onset group, atypical rash was significantly more frequent, typical rash and splenomegaly were significantly less frequent, white blood cell count and neutrophil ratio were significantly higher and serum IL-6 levels were significantly lower." (PMID 36494453, 2022). "The RAP99-LPS activity for immune activation was three times weaker than that of E. coli-LPS based on serum IL-6 concentrations, but twice as strong based on splenomegaly." (PMID 34113349, 2021). "This reduced splenomegaly in IL-6 KO infected mice is most likely related to the impaired recruitment of macrophages, dendritic cells, and neutrophils to the spleens in these mice." (PMID 33322581, 2020). "Hepatic swelling and splenomegaly were significantly more prevalent in the high IL-6 group than it was in the low IL-6 group (liver p < 0.001, spleen p = 0.020)." (PMID 31951598, 2020). "Taken together, these results demonstrate that IL-6 is required for early host resistance against Brucella infection in vivo, and indicate that IL-6 is required for the splenomegaly induced by B. abortus." (PMID 33322581, 2020). "GD patients affected with the most common visceral form of the disease have splenomegaly, hepatomegaly, bone lesions, cytopenia and chronic inflammation with elevated levels of IL-1, IL-6, IL-8 and TNF-α." (PMID 32872203, 2020).
Splenomegaly (continued). "We found that innate susceptibility to stress correlates with chronic inflammation, development of splenomegaly and a significant increase in the levels of circulating pro-inflammatory cytokines IL-1β and IL-6." (PMID 31707362, 2019). "The efficacy of treatment with a combination of genistein and exercise in the HFSD-fed mice on splenomegaly is further corroborated by reductions in body mass and plasma glucose and IL-6 levels also identified in this treatment group." (PMID 30348225, 2018). "IL6 and TNFα were found elevated in the serum of β−/− mice and splenomegaly was observed at 16 weeks of age33,34." (PMID 29849099, 2018). "In turn, IL-6 plasma levels correlated with BM fibrosis (p = 0.0056; r = 0.49), splenomegaly (p = 0.018; r = 0.46), and the number of circulating CD34+ cells (p = 0.029; r = 0.48) and correlated negatively with hemoglobin values (p = 0.047; r = −0.39)." (PMID 27672242, 2016). "We associated the plasma cytokine levels with disease presentation, plasma IL-6 levels negatively correlated with splenomegaly (Spearman rho -0.473, P< 0.02)." (PMID 26090964, 2015). "Co-application of Ad.pIXgp70 with Ad.IL5, Ad.IL6 or Ad.IL23 resulted in improved protection with high control over FV-induced splenomegaly and reduced viral loads." (PMID 24349306, 2013). "In vivo expression of IL-6 also led to obvious splenomegaly, consistent with the clinical observation that IL-6 serum concentration correlated with the spleen size as determined by ultrasound in patient with chronic liver disease." (PMID 21394214, 2011). "LLC mice had splenomegaly and elevated plasma IL‐6 levels compared with PBS." (PMID 40931444, 2025). "Thus, systemic inflammation (e.g., high levels of IL-6 and TNF-α) is associated with splenomegaly in LPS-treated mice." (PMID 37491335, 2023). "Indeed, the absence of RELMα led to increased circulating inflammatory cytokines including TNFα, IFNγ, IL-6 and IL-1α, and exacerbated splenomegaly." (PMID 34349768, 2021). "Treatment with genistein and exercise in combination may mitigate splenomegaly by beneficially affecting glucose and IL-6 pathways." (PMID 30348225, 2018). "Also, in MF, CRT levels highly correlate with bone marrow fibrosis, splenomegaly, and Interleukin-6 (IL-6) plasma levels." (PMID 27672242, 2016). "Observations from a transgenic mouse model demonstrate that mice expressing viral IL-6 but lacking mammalian IL-6 do not experience phenotypic changes (e.g., lymphoadenopathy, hypergammaglobulinemia, splenomegaly) associated with MCD." (PMID 23346088, 2012). "It has been demonstrated that splenomegaly is an IL-6-dependent phenotype in Lyn-deficient mice, however increases in IL-6 in Lyn-/- mice were not further exacerbated in the absence of GILZ and mRNA expression of GILZ and IL-6 were significantly positively correlated in human SLE." (PMID 33889157, 2021). "Additionally, IL-6 transgenic mice exhibit splenomegaly that is improved via the administration of anti-IL-6-receptor monoclonal antibody, suggesting that splenomegaly may be induced by increased IL-6." (PMID 31951598, 2020). "The data revealed a significant positive correlation between splenomegaly and the inflammatory markers such as CRP, IL‐6 and ferritin, reinforcing the strong link between splenic involvement and inflammation." (PMID 40637365, 2025). "In our murine model, we observed acute splenomegaly as well as significantly elevated IFN-γ, TNF, and IL-6 in the circulation of TAS2010-vaccinated mice." (PMID 37733817, 2023). "When the moribund DKO mice (12–14 months old) were sacrificed and compared with the age-matched triple-wild-type (TWT), IL-6–KO, and TKO mice, we found that the marked splenomegaly in DKO mice was reverted to the normal level in TKO mice." (PMID 35900794, 2022). "Hyperforin significantly inhibited imiquimod-induced splenomegaly, reduced serum levels of TNF-α and IL-6, and IL-17A in splenocytes and draining lymph nodes." (PMID 34025642, 2021).
Splenomegaly (continued). "The early acute infection of C57BL/6 or BALB/c mice with P. chabaudi (AS) is accompanied by splenomegaly, and a large but transient inflammatory response comprising elevated levels of cytokines such as IL-12, TNF-α, IL-6, and IFN-γ." (PMID 17555592, 2007). "LLC mice, independent of genotype, had splenomegaly and elevated plasma IL‐6 levels compared with PBS mice." (PMID 40931444, 2025). "Therefore, we examined the serum levels of the pro-inflammatory cytokines IL-1β, IL-6, and TNF-α in NCI-H460 xenograft model, which has the best response to GLPs in terms of tumor and splenomegaly inhibition." (PMID 36185644, 2022). "The correlations of serum IL-6 levels, which differed significantly between the young and middle-aged-onset group and the elderly-onset group, with the clinical manifestations, including typical or atypical rash, WBC count and neutrophil ratio, and splenomegaly, were analyzed." (PMID 36494453, 2022). "Furthermore, our results showed that serum IL-6 tended to be lower in patients with atypical skin rash and was significantly higher in patients with splenomegaly than in those without." (PMID 36494453, 2022). "Inflammation-mediated splenomegaly of C26-mice was inhibited by PM01183 for as long as the treatment lasted, without reducing IL-6, M-CSF or IL-1β in plasma." (PMID 32824440, 2020).
unstable angina (66 papers, 2007 to 2026). "Nevertheless, comorbid depressive ratings in unstable angina were not only associated with atherogenicity, IR, lowered zinc but also with increased IL-6 and calcium levels." (PMID 35055338, 2022). "The inflammatory response of the post-PCI state is characterized also by the increased levels of the cytokine IL-6; surprisingly, even diagnostic coronary angiography led to elevated plasma IL-6 in stable angina." (PMID 30973928, 2019). "Indeed, high IL-6 levels have been reported in patients with angina pectoris, and IL-6 levels have also been associated with the development of cardiovascular events." (PMID 39802992, 2024). "Similarly, in the present study, we demonstrated that positive association between IL-6 levels and the severity of coronary artery lesions were evaluated by the Gensini score in unstable angina." (PMID 35847417, 2022). "Also, elevated plasma levels of interleukin-6 (IL-6) have been associated with unstable angina and cardiovascular diseases, and IL-6 is related to other cardiovascular risk factors." (PMID 20407653, 2009). "The aim of this study is to investigate the acute inflammatory response in patients with stable angina by measuring the plasma levels of interleukin-6 (IL-6), a pro-inflammatory cytokine before and after DES implantation." (PMID 40026588, 2024). "One study that examined the relationship between blood carotenoids and IL-6 levels, an inflammatory marker in patients with CAD, found that only lutein/zeaxanthin showed an inverse correlation with IL-6 in individuals with stable angina." (PMID 39599645, 2024). "First, elevated serum levels of hs-cTnT allow for the stratification of patients with stable angina pectoris according to the stages of CAD with high precision, and the additional diagnostic value of NT-proBNP and IL-6 was only of secondary importance." (PMID 36014939, 2022). "Here, we similarly observed the higher plasma IL-6 level in unstable angina relative to those in the control group." (PMID 35847417, 2022). "Previous studies have demonstrated that the level of IL-6 in patients with ACS is significantly higher than that in patients with stable angina pectoris." (PMID 35847417, 2022). "High IL-6 levels are related to high body inflammatory state and adverse effects for multiple disease processes, such as unstable angina and septic shock." (PMID 34616230, 2021). "Patients with stable angina have significantly higher levels of cytokines, such as IL-6 and TNF-α, than do patients with normal coronary arteries." (PMID 34231707, 2021). "There is also a significantly positive correlation between plasma concentrations of NAMPT and high sensitivity C-reactive protein (hs-CRP) and IL-6 in the patients with stable angina pectoris." (PMID 26389889, 2015). "Increased circulating levels of IL-6 in patients with UA compared to patients with stable angina was first reported in 1996." (PMID 23991153, 2013). "Stenting/PCI was reported to trigger rapid, transient neutrophil activation, followed by the release of IL-6 and IL-8 in unstable angina; a similar post-PCI elevation of cytokines was reported also in stable angina." (PMID 23967262, 2013). "The evidence indicates while the overall effect on MACE was not significant in CHD patients, the new immunomodulatory drugs could reduced incidence of angina, revascularization, IL-6 levels, neutrophil count levels, and improve the LVEF." (PMID 41214504, 2025). "Patients with unstable angina have IL-6 levels about three times higher than healthy controls." (PMID 41511355, 2025). "This study investigated changes in IL-6 serum levels before and after coronary stenting in a carefully selected population only including patients with stable angina, demonstrating an increase in circulating IL-6 plasma levels immediately and 24 h after stent implantation." (PMID 40026588, 2024). "Secondly, IL-6 may be partly responsible for the hypofunction of circulating EPCs and severity of unstable angina patients." (PMID 35847417, 2022).
unstable angina (continued). "In patients with unstable angina, we discovered that activation of immune-inflammatory pathways (CRP and cytokines including IL-6) affects the physio-affective phenome of unstable angina, and that these effects are mediated by increased atherogenicity and insulin resistance." (PMID 36011997, 2022). "For example, the interleukin-6 (IL-6) serum concentrations of SCZ patients was confirmed by multiple studies to get significantly elevated, which was shown to be associated with clinical progression of unstable angina and increased risk of MI." (PMID 34149793, 2021). "Moreover, in patients admitted to the hospital for unstable angina, increased IL-6 levels are predictive of prolonged hospitalization and worse clinical outcomes." (PMID 34760045, 2021). "Moreover, IL-6 levels are significantly higher in patients with ACS than in patients with stable angina." (PMID 34231707, 2021). "Bao Xin decoction (another formula to treat PSCS with IHD) was effective in curing CAD with stable angina pectoris and acting by inhibiting serum interleukin 6 (IL-6), intercellular adhesion molecule 1 (ICAM-1) and tumor necrosis factor-α (TNF-α) levels and decreasing inflammatory reactions." (PMID 29403392, 2018). "In patients with unstable angina, oxLDLs may contribute to monocyte overproduction of some cytokines and above all to that of IL-6 and IL-1β, by upregulating TLR4 expression." (PMID 25757594, 2015). "Similarly, a decrease of plasma lactoferrin and myeloperoxidase and increase of IL-6 were observed during 6–12 hours after stenting in unstable angina." (PMID 23967262, 2013). "Particularly in patients with unstable angina (UA), plasma IL-6 levels are three times higher than those of healthy controls and are closely related to the concentration of high-sensitivity C-reactive protein (hs-CRP), indicating that IL-6 may be involved in the early acute-phase reaction of ACS." (PMID 34231707, 2021). "Also they described elevated levels of IL-6 in unstable angina." (PMID 23028694, 2012). "Secondary outcomes are cTnT, NT-proBNP, inflammatory/endothelial biomarkers (hs-CRP, IL-6, MMP-9, VEGF, HMGB1), and angina-related parameters (attack frequency, symptom severity)." (PMID 41195123, 2025). "Circulating IL-6 and IL-1β levels were found to be higher in patients with AMI compared to stable angina." (PMID 38256155, 2024). "Shexiang Baoxin pills combined with conventional WM have a significant effect on patients with angina pectoris of CAD, which can effectively reduce the levels of IL-6 and hs-CRP and inhibit the inflammatory response of patients." (PMID 37484810, 2023). "Among the particularly excellent compounds for unstable angina, liquiritin (MOL004903) reduces mRNA expression of TNFα, IL-6, and IL-1β, inhibits inflammatory cell migration, suppresses oxidative stress and apoptosis in the heart, and improves metabolism." (PMID 35140797, 2022). "Secondary outcome parameters: other circulating inflammatory markers (including IL-6, TNFα, VCAM-1, CD40, sCD40L, MCP-1, and MMP-9), improvement in symptoms of angina and blood stasis syndrome, and safety." (PMID 23983803, 2013). "We did observe a significantly lower concentration of both IL-6 and TNF-α in the healthy controls compared to the patients with stable angina (p = 0.001 and p = 0.03, respectively)." (PMID 23091596, 2012). "Comparisons of differing association between the two endpoints showed significant/marginally significant differences in the relationships between the inflammatory biomarkers (CRP, IL-6, fibrinogen), fibrin D-dimer and MI/CHD death and uncomplicated angina." (PMID 19682232, 2009). "The outcomes assessed included the efficacy in treating angina pectoris, overall efficacy, efficacy on clinical symptom and ECG, frequency of angina attacks, duration of angina attacks, incidence of cardiovascular events, TC, TG, LDL-C, HDL-C, hs-CRP, IL-6, and dosage of nitroglycerin." (PMID 40621069, 2025).
unstable angina (continued). "Recently, we found that Tan IIA significantly reduced levels of serum inflammatory cytokines, such as high-sensitivity C-reactive protein (hs-CRP), interleukin-6 (IL-6), and monocyte chemoattractant protein-1 (MCP-1) in patients with unstable angina/non-ST segment elevation myocardial infarction." (PMID 31402870, 2019).